STAT3 (signal transducer and activator of transcription 3)
Diseases named in the same sentence as STAT3 in open-access papers (continued):
Sharing a sentence is not in itself a finding about the gene and the disease.
sarcoma (continued). "Expression of the dominant-negative Stat3 and treatment of STA-21 inhibited cell viability and growth and induced apoptosis through caspases 3, 8 and 9 pathways in human sarcoma cell lines expressing elevated levels of phosphorylated Stat3." (PMID 17598902, 2007). "Additionally, anlotinib has been shown to potentiate PD-1 blockade efficacy by downregulating STAT3-driven PD-L1 expression in sarcoma models." (PMID 41001046, 2025). "In veterinary medicine, STAT3 expression has been reported in canine, feline, and equine mammary gland tumors, equine renal hemangiosarcoma, feline oral squamous cell carcinoma, canine diffuse large B-cell lymphoma, and feline injection-site sarcomas." (PMID 35836213, 2022). "Likewise in human patients and mouse models, prior studies evaluating the NF-λB/IL-6/STAT3 axis in other types of sarcoma have reported increased IL-6 signaling and attenuation of tumorigenesis following treatment with IL-6 inhibitors." (PMID 27105514, 2016). "For example STAT3 is an oncoprotein in sarcoma, whilst STAT1 is a tumour suppressor." (PMID 26909593, 2016). "The use of STAT3 blockage in combination with panHER inhibition in cancers including epithelial cancers and sarcoma, with HER-family hyper-activation and resistance to panHER inhibitor, is a new direction to explore and has potential in clinical cancer therapy in the future." (PMID 25674538, 2015). "Moreover, STAT3 inhibition via a novel small molecule STAT3 inhibitor (STA-21) or a dominant negative form of STAT3 resulted in inhibition of proliferation and apoptosis of sarcoma cell lines expressing high levels of phospho-STAT3." (PMID 19284568, 2009). "Inhibition of Stat3 signaling in sarcomas may represent an effective new treatment strategy for this type of human cancer." (PMID 17598902, 2007). "Since elevated levels of Stat3 phosphorylation was found in sarcoma tissues and cell lines, we subsequently investigated the role activated Stat3 may play in cell growth or survival of sarcoma cell lines." (PMID 17598902, 2007). "We also investigated the status of p-Stat3 in sarcoma cell lines." (PMID 17598902, 2007). "The mechanisms underlying the elevated Stat3 phosphorylation in these sarcoma tissues are not clear." (PMID 17598902, 2007). "Furthermore, the activated Stat3 pathway is important for cell growth and survival of human sarcoma cells." (PMID 17598902, 2007). "Inhibition of Stat3 signaling in sarcomas may represent an effective treatment strategy for these types of cancer." (PMID 17598902, 2007). "So, blocking IL-6/STAT3 may be an excellent approach used to suppress sarcoma metastasis." (PMID 36979391, 2023). "In vitro experiments using sarcoma (SRC) agonists and inhibitors were performed to investigate the impact of ACNO therapy on the expression of SRC, STAT3, and other proteins in HaCaT cells." (PMID 40066291, 2025). "JNK/p38-MAPK, PVT1/ERG, programmed cell death 4 (PDCD4)/ERK1/2, SOCS3/JAK2/STAT3, TGF-β/COL6A1, IL6/STAT3, PI3K/Akt/mTOR, and Hedgehog in exosomes regulate genes or signaling pathways to promote the migration and metastasis of sarcoma cells." (PMID 36979391, 2023). "After JAK2/STAT3 inhibition, we observed a decrease in c-MYC protein expression in sarcoma cells treated with LFU and PTX combination in vitro." (PMID 36582521, 2022). "LFU combined with PTX significantly induced cell apoptosis, and blocked the cell cycle of sarcoma cells in G2/M phase, and furthermore, inhibited the activation of JAK2/STAT3 signaling pathway." (PMID 36582521, 2022). "STAT3 was mostly involved in the activation of EMT, hormone Estrogen Receptor (ER), rat sarcoma/mitogen activated protien kinase RAS/MARK, and Receptor tyrosine kinase (RTK), while the major inactivated pathways were cell cycle and DNA damage response." (PMID 36176415, 2022).
sarcoma (continued). "We previously investigated the allosteric small molecule STAT3 inhibitor, LLL12, demonstrating that it inhibits proliferation and induces apoptosis in childhood sarcoma cell lines, although this drug had poor pharmacokinetic properties." (PMID 28750090, 2017). "In our attempt to check a panel of suppressive molecules in the gene level, it was found more or less downregulation of Arginase 1, iNOS2, STAT3, IL-10, IDO, MMP9 and TGFβ in MDSCs from NLGP-treated surgically sarcoma removed mice." (PMID 28414726, 2017). "The GEPIA website also identified a positive correlation between STAT3 and LINC00662 in sarcoma." (PMID 36334221, 2023). "Notably, epimedokoreanin B also suppressed cell proliferation by blocking STAT3 activation in Saos-2 human sarcoma and LM8 mouse sarcoma cell lines." (PMID 32256354, 2020). "Although treatment with LY5 inhibits the activation of STAT3 in metastatic pulmonary lesions of sarcoma xenografts, it failed to suppress lung metastasis in vivo." (PMID 32754598, 2020). "In contrast, almost complete knockdown of STAT3 in the sarcoma cell lines used in this study failed to decrease proliferation in any cell line except RH30." (PMID 28750090, 2017). "Recently, the presence of increased ALDH1 activity allowed the identification of a subpopulation of human sarcoma cell lines with stem cell properties, including high level of expression of stem cell genes such as NANOG, OCT3/4, STAT3 and SOX2, and resistance to chemotherapy." (PMID 23734203, 2013). "We targeted activated Stat3 pathways with rAd/dnStat3 and STA-21 in sarcoma cell lines." (PMID 17598902, 2007). "However, its lack of biologic activity in vivo combined with data generated from siRNA studies downregulating STAT3 expression in sarcoma cell lines strongly suggested that its effects in vitro were not tied to inhibition of STAT3 phosphorylation." (PMID 28750090, 2017). "However, RNAi-mediated knockdown of STAT3 did not phenocopy the biologic effects of LY5 in sarcoma cell lines." (PMID 28750090, 2017).
small cell lung carcinoma (32 papers, 2007 to 2025). Small cell lung cancer (SCLC) is a highly aggressive malignant neoplasm, accounting for 10-15% of lung cancer cases, characterized byrapid growth, and early metastasis. "Additionally, EPHA3 has been associated with the regulation of multi-drug resistance in small cell lung cancer via the PI3K/BMX/STAT3 signaling pathway." (PMID 29383146, 2017). "We find that overexpression of TARS1 supports non–small cell lung cancer cell proliferation in vitro, tumor formation of xenografts in mice, and hyperactivity of STAT3." (PMID 41380973, 2025). "RES demonstrates potential in overcoming drug resistance in small cell lung cancer by inhibiting the STAT3/VEGF pathway and P‐glycoprotein function." (PMID 40860906, 2025). "Previous studies have demonstrated that the phosphorylation of STAT3/MYC by CSF2 regulates the phenotypic plasticity of small cell lung cancer." (PMID 38817867, 2024). "For instance, one study showed that citral inhibited the activity of the protein STAT3 in small-cell lung cancer, leading to decreased cell viability and increased apoptosis." (PMID 38041055, 2023). "Studies have shown that in the microenvironment of interleukin (IL)-23-mediated tumor inflammation, the STAT3/VEGF pathway activates to induce resistance to doxorubicin in small-cell lung cancer (SCLC) cells." (PMID 35684449, 2022). "Previous studies have shown that STAT3 is involved in tumor proliferation and drug resistance in small cell lung cancer." (PMID 35885009, 2022). "Small cell lung cancer cell lines present constitutive phosphorylation of STAT3, and in the reference cell lines NCI-H69 and NCI-H82 constitutive phosphorylation was further increased by CXCL12 stimulation." (PMID 19455144, 2009). "Curcumin has been shown to effectively inhibit STAT3 phosphorylation in small cell lung cancer by downregulating downstream regulatory proteins of STAT3, which contributes to the inhibition of cell proliferation, diminished cell colony formation, and reduced cell migration and invasion." (PMID 37700835, 2023). "In cell‐free enzymatic assays, TPCA‐1 displays 22‐fold selectivity for IKK‐2 over IKK‐1 and a >550‐fold selectivity over other kinases, including MAP kinases and JNK kinases 32, though a recent study showed that in non–small cell lung cancer cell lines TPCA‐1 also inhibited STAT‐3 phosphorylation." (PMID 27023358, 2016). "Indeed, it has been shown that the STAT3-dependant growth arrest signal is inactivated in small cell lung cancer cells, resulting in growth promotion." (PMID 20187943, 2010). "By using the specific antibody against phosphorylated STAT3 and western blot, we, here, show that STAT3 is constitutively activated in A549 human non-small-cell lung cancer cell line, which was consistent with our previous observations in human pulmonary giant cell carcinoma PG cell line." (PMID 17683579, 2007). "By activating STAT3, TAMs and small-cell lung cancers could jointly promote tumor progression." (PMID 36838599, 2023). "Interestingly, erlotinib, as an RTK inhibitor, increases STAT3 phosphorylation (Tyr705) in EGFR-mutant ono-small-cell lung cancer (NSCLC) cells through an autocrine loop, whereas knockdown of STAT3 decreases erlotinib-resistant colony numbers in the presence of erlotinib." (PMID 32872659, 2020). "More recently, small cell lung carcinoma (SCLC) cells lines and primary SCLC tumors show increased phosphorylation of STAT3, and treatment of SCLC cell lines with SDF-1α further increased STAT3 phosphorylation." (PMID 25514788, 2014). "Importantly for human metastatic lung adenocarcinoma and small cell lung cancer (SCLC), it has been reported that cyclin D1 expression is regulated by Cav1 expression and aberrant activation of the signal transducer and activator of transcription-3 (STAT3)." (PMID 23521716, 2013).
small cell lung carcinoma (continued). "Not only in NSCLC but also in the small cell lung carcinoma (SCLC) cell lines, NCI-H446 and NCI-1688, curcumin at 15 μ M plays notable role to prevent migration, invasion as well as angiogenesis via Janus Kinase-STAT3 signaling pathway." (PMID 25566531, 2014). "However, the mechanism by which dysregulated STAT3 signaling contributes to the progression of human small cell lung cancer (SCLC) has not been elucidated." (PMID 22662257, 2012).
eczema (31 papers, 2014 to 2026). "The autosomal dominant form is most commonly associated with pathogenic variants in STAT3 that impair Th17/IL-1, predisposing to Staphylococcus aureus and Candida infections, with dysregulated IL-6/IL-10 contributing to eczema-like lesions." (PMID 41378312, 2026). "All patients carried a heterozygous STAT3 mutation and fulfilled the characteristic findings of STAT3-HIES consisting of eczema, elevated serum-IgE, recurrent infections, and associated skeletal findings." (PMID 32912316, 2020). "STAT3 hyper-IgE syndrome is a rare primary immunodeficiency associated with eczema, recurrent infections, and high serum IgE levels." (PMID 32912316, 2020). "For refractory eczema, emerging biologic therapies such as the IL-4/IL-13 receptor antagonist dupilumab have shown promising results in some patients with STAT3-HIES." (PMID 41458089, 2025). "Autosomal-recessive LOF mutations in ZNF341 phenocopy STAT3-HIES, causing elevated IgE, eosinophilia, eczema, and recurrent bacterial and fungal infections." (PMID 40666020, 2025). "As the primary bioactive alkaloid in Sophorae Flavescentis Radix, matrine ameliorates skin pathology in eczema mouse models by reducing STAT3 mRNA levels, contributing to its anti-eczema activity." (PMID 40612058, 2025). "The M660A STAT3 variation was identified in a patient with newborn skin rash and eczema, infections, and typical facial abnormalities, and known mutations on the same residue (M660) have been reported to be pathogenic." (PMID 37081481, 2023). "Eczema is also a common manifestation of T-cell disorders, including Wiskott Aldrich Syndrome (WAS), autosomal dominant STAT3 deficient Hyper IgE syndrome (STAT3-HIES) and DOCK8 deficiency." (PMID 35371103, 2022). "Early onset eczema was 37% in our STAT3 HIES cohort but was observed in larger numbers the French cohort (48%)." (PMID 33717144, 2021). "While other pathways (e.g., JNK and STAT3) contribute to eczema, p38/NF-κB and JAK1-STAT6 were prioritized due to their clinical relevance—both are validated therapeutic targets in refractory eczema, making them ideal for evaluating MTMZM's translational potential." (PMID 40933470, 2025). "A heterozygous STAT3 c.1915C > T missense mutation—unreported in clinical case literature—was identified, highlighting HIES as a key differential diagnosis in patients with recurrent skin infections, eczema, and related symptoms." (PMID 41458089, 2025). "In contrast to the model group, SYXL (300, 900 μg/mL) inhibited the phosphorylation of JAK2 and STAT3, suggesting that suppression of JAK/STAT pathway activation may represent a key mechanism underlying SYXL’s anti-inflammatory and anti-eczema properties." (PMID 40612058, 2025). "Here, we report a novel missense variant of unknown significance in the DNA-binding domain of STAT3 in a patient who experienced hypogammaglobulinemia, lymphadenopathy, hepatosplenomegaly, immune thrombocytopenia, eczema, and enteropathy over a 35-year period." (PMID 39836489, 2025). "In patients with severe allergic phenomena (eczema, eosinophilia, food allergies) measuring IgE levels can also be helpful in identifying certain disorders, i.e., Hyper IgE syndromes such as DOCK8 deficiency, STAT3-HIES and PGM3 deficiency." (PMID 35371103, 2022). "In addition to eczema, elevated serum-IgE, and recurrent infections, STAT3-HIES patients suffer from characteristic facies, midline defects, and retained primary teeth." (PMID 32912316, 2020). "The patients have clinical features with greater similarity to that of STAT3-HIES, presenting with recurrent infections, bronchiectasis, eczema, high IgE, eosinophila, impaired acute-phase response, as well as skeletal and connective abnormalities (craniosynostosis and scoliosis)." (PMID 36140582, 2022).
eczema (continued). "In this study, we investigated the activation of STAT3 in cancer cells by immunohistochemistry and found that the frequency of phosphorylated STAT3-positive cancers was not significantly different from that in the eczema group." (PMID 34679602, 2021). "ELISA and Western blotting analyses revealed that SYXL alleviated eczema-like skin lesions induced by DNCB in animal models, reversed histopathological abnormalities, curbed the expression of pro-inflammatory cytokines IL-1β, IL-6, and TNF-α, and inhibited the phosphorylation of JAK2 and STAT3." (PMID 40612058, 2025).
myeloproliferative neoplasm (30 papers, 2009 to 2026). A clonal hematopoietic stem cell disorder, characterized by proliferation in the bone marrow of one or more of the myeloid (i.e., granulocytic, erythroid, megakaryocytic, and mast cell) lineages. "The expression and mutation of JAK2 is associated with glucose metabolic reprogramming in myeloproliferative neoplasms, type 3 diabetes‐induced liver tumors and mesenchymal stem cells, and the JAK2/Stat3 pathway facilitates the progression of HCC." (PMID 40693878, 2025). "STAT3 has been reported as a part of the JAK2/STAT3/STAT5/PD-L1 axis which can drive immune escape in myeloproliferative neoplasms." (PMID 33371351, 2020). "The utility of STAT3 inhibitors has largely been confined to myeloproliferative disorders, in part due to their poor blood–brain barrier (BBB) penetration." (PMID 31399589, 2019). "As with STAT3, genetic alterations in the STAT5A gene has been implicated in myeloproliferative disorders and linked to hematopoietic stem cell proliferation." (PMID 31783691, 2019). "Nevertheless, upregulation of SOCS3 has been reported in CTCL and other malignancies in association with elevated JAK-STAT signalling, and in JAK2V617F positive myeloproliferative disorders together with STAT3 and STAT5B, consistent with our findings." (PMID 23372669, 2013). "The constitutively active JAK2 mutant V617F is found in many patients with myeloproliferative diseases, and constitutively phosphorylated STAT3 is found in many solid tumours and haematopoietic malignancies." (PMID 19455144, 2009). "In addition, JAK2 is the overlapping gene, and disregulation of the IL6/JAK2/STAT3 signalling pathways can lead to increased cellular proliferation and myeloproliferative neoplasms of hematopoietic stem cells." (PMID 33126852, 2020). "Notably, high PD-L1 expression in monocytes has also been reported in non-Philadelphia chromosome myeloproliferative neoplasms with a JAK2 V617F mutation via STAT3/STAT5-dependent transcriptional induction." (PMID 34508131, 2021). "By accelerating STAT3 phosphorylation and increasing NOTCH-1 signaling, loss-of-function variants in SH2B3 have been linked to the oncogenesis of myeloproliferative neoplasms (MPN), early T-ALL, Ph-like ALL, B-ALL, and non-malignant hematological disorders." (PMID 36834692, 2023). "Interestingly, another recent study (n = 7) discovered that HSP90 inhibition disrupted JAK-STAT signalling by potently decreasing JAK2 expression and the phosphorylation of STAT3 and STAT5 in patients with myeloproliferative neoplasms." (PMID 38274815, 2023). "Loss-of-function mutations in SH2B3 are reported to play an important role in the oncogenesis of myeloproliferative neoplasms (MPN), early T-ALL, Ph-like ALL, B-ALL and nonmalignant hematological diseases by accelerating STAT3 phosphorylation and increased NOTCH-1 signaling." (PMID 32085659, 2020).